ILK (integrin linked kinase)
Diseases named in the same sentence as ILK in open-access papers (continued):
Sharing a sentence is not in itself a finding about the gene and the disease.
ovarian carcinoma (37 papers, 2005 to 2025). A malignant neoplasm originating from the surface ovarian epithelium. "And the association between ILK and cell survival and deterioration of ovarian cancer has also been reported before." (PMID 35379775, 2022). "The association between worse survival in patients with ovarian cancer who exhibit ILK upregulation is also true for these different cancers types as well." (PMID 33256002, 2020). "Expression-based survival analysis using the Kaplan–Meier (KM) plotter database revealed significant associations between potential ILK target genes and ovarian cancer prognosis." (PMID 32260415, 2020). "The molecular and biological effects of siRNA-mediated ILK targeting in cisplatin-resistant ovarian cancer and the identification of associated downstream effectors have not been fully explored." (PMID 32260415, 2020). "By using Kaplan–Meier analysis of publicly available mRNA expression (gene chip and RNA-Seq data) we further show that several genes differentially altered upon ILK depletion are significantly associated with survival outcomes in ovarian cancer." (PMID 32260415, 2020). "By activating integrin-linked kinase (IL-K), the integrin αv subunit promotes growth and proliferation of ovarian cancer cells, and mediates their adhesion and migration." (PMID 21747684, 2011). "Recent studies have also linked ILK expression to tumor grade of prostate, gastric or ovarian carcinomas." (PMID 15631637, 2005). "In ovarian cancer, ILK expression has been previously associated with tumor progression." (PMID 32260415, 2020). "Specific chemical inhibitors against four molecules linked with EMT—that is, Smad 2/3, ILK, AP-1, and SP-1—were added to ovarian cancer cells prior to their exposure to the malignant ascites to identify the signaling pathway(s) responsible for the induction of this process." (PMID 30609691, 2019). "Although there are currently no clinical trials directly targeting LIMS2, its binding partner ILK has been identified as a potential therapeutic target in ovarian cancer." (PMID 40755754, 2025). "Compared with other cancer cell lines, ovarian cancer cells displayed a notable dependency on TOR2A and integrin-linked kinase." (PMID 40953111, 2025). "In ovarian cancer, TGM2 interacts and activates the integrin-linked kinase (ILK) through phosphorylation at ILK Ser246, which subsequently activates β-catenin through the phosphorylation of glycogen synthase kinase-3α/β (GSK3α/β)." (PMID 39115570, 2024). "Results have shown that ILK expression increased SNAIL1 protein levels and silence of ILK decreased SNAIL1 protein levels in ovarian cancer cells." (PMID 35379775, 2022). "Researchers also observed reduced cisplatin-resistant cell growth and invasion ability and increased apoptotic response after siRNA-mediated silencing of ILK expression in ovarian cancer cells." (PMID 35089438, 2022). "We showed that β-catenin, GSK-3β, and AKT, and especially ILK are important molecules in the binding of fibronectin to ovarian cancer cells." (PMID 35317111, 2021). "In recent years, various studies have been carried out on the silencing and inhibition of the ILK gene in ovarian cancer." (PMID 35317111, 2021). "It was reported that ILK is overexpressed in many cancers, such as colon, prostate, and ovarian cancers." (PMID 35317111, 2021). "This study examines the impact of integrin-linked kinase (ILK), protein kinase B (AKT), glycogen synthase kinase-3β (GSK-3β), and β-catenin signal molecules in SKOV-3 ovarian cancer cells adhered to fibronectin." (PMID 35317111, 2021). "In this studey, we demonstrated the expression of αv and β1 integrin subunits, which is known to be effective on the ILK signaling pathway, in ovarian cancer cells, SKOV-3." (PMID 35317111, 2021). "As the dissolving factors in the peritoneal tumor fluid mediate continuous overexpression of ILK, ILK expression increases in the progression of ovarian cancer." (PMID 35317111, 2021).
ovarian carcinoma (continued). "As a critical adaptor and mediator protein in the normal development of numerous tissues, ILK also plays important role in regulating cell adhesion junction, and ILK is critical for the invasiveness of human ovarian cancer cells." (PMID 33854551, 2021). "A study (2004) reported that immunoreactive (ir) ILK is an ovarian tumor antigen and that the expression of irILK in the serum of patients with grade 1,2,3 ovarian cancers is 6–9 times greater than the serum of normal patients with benign tumors." (PMID 35317111, 2021). "Increased levels of ILK, a serine/threonine kinase and adaptor protein, have been well documented in different tumor types, including ovarian cancer." (PMID 32260415, 2020). "Targeting ILK abrogates the invasive potential of ovarian cancer cells, induces apoptosis, and decreases cell viability." (PMID 32260415, 2020). "ILK inhibition in ovarian cancer, however, has been shown to affect apoptotic, proliferative, and metastatic pathways." (PMID 33256002, 2020). "We also observed that transfection of ILK-siRNA reduced the invasive potential of cisplatin-resistant ovarian cancer cells, which is in agreement with previous studies showing that ILK activity modulates the pro-metastatic behavior of ovarian cancer." (PMID 32260415, 2020). "Ovarian cancer patients with high ILK expression had shorter PFS compared to patients with cancer that expressed lower ILK." (PMID 33256002, 2020). "To further assess the signaling pathways altered as a result of ILK-siRNA transfection in cisplatin-resistant ovarian cancer cells, we performed a transcriptome-wide analysis by RNA sequencing (RNA-Seq)." (PMID 32260415, 2020). "As CAFs promote cancer metastasis, our results showing that ILK depletion leads to ARHGEF26-AS1 downregulation suggest additional roles for ARHGEF26-AS1 in cisplatin-resistant ovarian cancer." (PMID 32260415, 2020). "To assess the clinical significance of p-ILK expression in ovarian cancer, we performed immunohistochemical (IHC) analysis in normal ovary and ovarian cancer tissue sections." (PMID 32260415, 2020). "Overall, these observations suggest that ILK regulates the JNK/c-JUN pathway in cisplatin-resistant ovarian cancer via modulation of DUSP8, MARVELD3, PDCD4, MAPK8IP1, MAPK8IP2, and HIPK3." (PMID 32260415, 2020). "Western blot analysis showed that phosphorylation levels of ILK were higher in cisplatin-resistant compared with cisplatin-sensitive ovarian cancer cells." (PMID 32260415, 2020). "Our preliminary results showing ILK inhibition in epithelial ovarian cancer highlight a novel pathway for the development of small-molecule inhibitors of this pathway for ovarian cancer treatment." (PMID 33256002, 2020). "Early reports show that subcutaneous injection of ovarian cancer cells transfected with either ILK-short hairpin RNA (shRNA) or ILK-antisense oligonucleotides (ASOs) suppresses tumor formation and growth in vivo." (PMID 32260415, 2020). "Taken together, results from this study support ILK as an attractive target for ovarian cancer and provide potential ILK downstream effectors with prognostic and therapeutic value." (PMID 32260415, 2020). "Further immunohistochemical analysis of ovarian cancer patient samples showed a significant increase in phosphorylated ILK levels in the tumor tissue when compared to normal ovarian epithelium." (PMID 32260415, 2020). "Further studies are required to fully understand the contribution of ILK downstream effectors to cisplatin resistance in ovarian cancer." (PMID 32260415, 2020). "Similar to our results, ILK activity stimulates invasion and migration of the SKOV3 human ovarian cancer cell line, whereas ILK depletion by shRNA (short hairpin RNA) abrogates the invasive potential of SKOV3 cells." (PMID 32260415, 2020). "We also measured the phosphorylation levels of AKT (p-AKT; Ser 473)—a downstream target of ILK —in cisplatin-resistant ovarian cancer cells and their respective cisplatin-sensitive counterparts." (PMID 32260415, 2020).
ovarian carcinoma (continued). "The purpose of this study was to investigate the molecular and biological effects of targeting ILK in cisplatin-resistant ovarian cancer." (PMID 32260415, 2020). "Transfection of ILK-siRNA into cisplatin-resistant ovarian cancer cells induced long-term effects on cell growth, short-term effects on cell viability in combination with cisplatin treatment, and increased caspase-3 activity." (PMID 32260415, 2020). "Other studies have shown that ILK activity modulates the pro-metastatic behavior of ovarian cancer by stimulating cell invasion and migration." (PMID 32260415, 2020). "The efficacy of CP22 in epithelial ovarian cancer cell lines and in vivo patient-derived xenografts validates the ability of small-molecule inhibitors to successfully target the ILK pathway in ovarian cancer and warrants further study." (PMID 33256002, 2020). "In this study, we assessed the phosphorylation levels of ILK in ovarian cancer cell lines and tissue samples and investigated the effects of targeting ILK in cisplatin-resistant ovarian cancer." (PMID 32260415, 2020). "ILK silencing has also been shown to reduce the expression of wnt ligands (wnt3a, wnt4, and wnt5a) and β-catenin in epithelial ovarian cancer cells." (PMID 33256002, 2020). "Results from RNA-Seq analysis of ILK-siRNA-transfected ovarian cancer cells showed significant changes in the expression of cancer-associated molecules including protein-coding genes and lncRNAs." (PMID 32260415, 2020). "Inhibition of ILK activity or expression significantly reduced ovarian cancer cell adhesion to the meso-mimetics." (PMID 26959113, 2016). "Silencing of ILK expression using shRNA in ovarian cancer cells suppressed anti-apoptotic bcl-2 and increased pro-apoptotic bax expression, leading to enhanced apoptosis." (PMID 26959113, 2016). "It has previously been reported that expression of ILK correlates with the progression of ovarian cancer, with enhanced expression found in high-grade human tumors compared to weak staining in low-grade lesions." (PMID 26959113, 2016). "In ovarian cancer, studies have shown up-regulated ILK expression compared to benign tumors and normal ovarian epithelium; additionally, a direct relationship between ILK expression and ovarian tumor grade has been demonstrated." (PMID 26959113, 2016). "Together with the results of the current study, recent reports demonstrate the potential efficacy of ILK inhibition in ovarian cancer." (PMID 26959113, 2016). "Reduction of ILK activity with QLT0267 or ILK expression with siRNA significantly inhibited ovarian cancer cell invasion of meso-mimetic cultures." (PMID 26959113, 2016). "The objective of the current study was to evaluate the expression of ILK and MT1-MMP in ovarian cancer cells and tissues and to examine the effect of ILK inhibition on pro-metastatic ovarian cancer cell behavior." (PMID 26959113, 2016). "In ovarian cancer cells, βArr1 is linked with the endothelin-1-induced activation of Akt, GSK-3β in integrin-linked kinase (ILK) activation." (PMID 23418490, 2013). "Correlation between ILK expression with tumor stage and patient survival has been reported in various malignancies including prostate cancer, colon cancer and ovarian cancer." (PMID 21347395, 2011). "We have recently demonstrated increased ILK expression in high-grade ovarian tumours and epithelial ovarian cancer cell lines." (PMID 18349831, 2008). "The apparent increase in PDK1 expression in high-grade ovarian carcinomas is consistent with our previously reported parallel increase in ILK expression with increasing grade of ovarian carcinomas." (PMID 18349831, 2008). "We have also demonstrated enhanced expression of ILK, a putative target gene of PPARβ, in high-grade ovarian tumours and the presence of cell-free irILK in the serum and ascites of ovarian cancer patients." (PMID 18349831, 2008).
ovarian carcinoma (continued). "Recent studies have found that IQ-domain GTPase-activating protein 1 (IQGAP1), integrin-linked kinase (ILK), and the scaffold protein β-arrestin are required for ETAR-mediated MMP production, invadopodia formation, migration, and invasion in ovarian cancer cells." (PMID 38785410, 2024). "Coleman with colleagues further investigated the molecular and biological effects of targeting ILK in cisplatin-resistant ovarian cancer and identified multiple target genes involved in cell growth, apoptosis, invasion, and metastasis, including those encoding noncoding RNAs." (PMID 35089438, 2022). "In addition, ILK expression is upregulated in ovarian cancer, and it has a positive correlation with tumor development." (PMID 35481240, 2022). "All these data further confirmed that ILK regulates SNAIL1 expression in ovarian cancer." (PMID 35379775, 2022). "The in vivo tumorigenesis of human ovarian cancer cells is suppressed by silencing the ILK gene." (PMID 35481240, 2022). "ILK was significantly highly expressed in the tissues of ovarian cancer patients at the ages older than 50, in III-IV stages, or with lymphatic metastases than in the tissues of ovarian cancer patients younger than 50, I-II stages, or without lymphatic metastases, respectively." (PMID 35379775, 2022). "In this study we further examined whether SNAIL1 expression is dependent on ILK expression in ovarian cancer." (PMID 35379775, 2022). "In addition, expression of ILK in ovarian cancer tissues was demonstrated to be correlated with tumor stages and lymphatic metastases clinically." (PMID 35379775, 2022). "In addition, expression of ILK in ovarian cancer tissues was much higher than that in normal ovarian epithelial tissues." (PMID 35379775, 2022). "It has been also found that ILK regulates the metastatic behavior of ovarian cancer cells." (PMID 35317111, 2021). "To assess whether the differentially expressed transcripts identified upon ILK targeting are clinically relevant in ovarian cancer, we conducted survival analysis using Kaplan–Meier plotter (KM plotter)." (PMID 32260415, 2020). "Downregulation of ILK using siRNA knockdown results in reduced adhesion to and invasion of collagen gels and organotypic meso-mimetic cultures, suggesting that ILK is integral to the development of metastatic disease in ovarian cancer." (PMID 33256002, 2020). "Although reports suggest that integrin-linked kinase (ILK) is a potential target for ovarian cancer treatment, identification of ILK downstream effectors has not been fully explored." (PMID 32260415, 2020). "siRNA knockdown of ILK reduced SKOV3 cell proliferation: To determine whether knockdown of ILK expression affects ovarian cancer cell proliferation, we transfected SKOV3 cells with ILK siRNA and measured the number of viable cells by SRB assay." (PMID 33256002, 2020). "Moreover, increased ILK activation has been shown to protect platinum-resistant ovarian cancer cells from cisplatin-induced apoptosis." (PMID 32260415, 2020). "Next, we studied whether targeting ILK reduces cell growth and the invasive ability of cisplatin-resistant ovarian cancer cells." (PMID 32260415, 2020). "Murine models of patient-derived ovarian cancer tissue that have undergone next-generation sequencing are currently under development and will provide insight into the molecular profiles of tumors that respond to ILK inhibition." (PMID 33256002, 2020). "ILK is expressed in ovarian cancer cell lines: To determine whether ILK is expressed in ovarian cancer cell lines, Western blots in SKOV3 and OV90 ovarian cancer cell lines were performed and compared to non-cancerous COS7 cells." (PMID 33256002, 2020). "ILK is overexpressed in ovarian cancer relative to normal ovarian tissue: To identify reliable therapeutic targets for advanced ovarian cancer, high-grade treatment-naïve ovarian cancer specimens, and pair-matched adjacent normal ovarian tissues were obtained from the CHTN." (PMID 33256002, 2020).
ovarian carcinoma (continued). "Results of the current study show that knockdown or pharmacologic inhibition of ILK in ovarian cancer cells also modulates MCA dynamics, inhibits adhesion to collagen and mesothelial cells, and blocks invasion of 3-dimensional collagen gels as well as organotypic meso-mimetic cultures." (PMID 26959113, 2016). "It has previously been reported that ILK is expressed in advanced ovarian cancers." (PMID 26959113, 2016). "Recently, we have shown that ascites enhances the expression of integrin-linked kinase and its downstream Akt pathway in ovarian cancer cells but not in HOSE cells." (PMID 15798771, 2005). "Therefore, whether SNAIL1 expression is dependent on ILK expression was examined in ovarian cancer in this study." (PMID 35379775, 2022). "Curiously, the elevated ILK level in serum might be considered as a marker of various cancers, such as malignant pleural mesothelioma, non-small cell lung cancer, esophageal squamous cell carcinoma, and ovarian carcinoma." (PMID 35089438, 2022). "Therefore, changes in the expression of these genes following siRNA-mediated ILK depletion in cisplatin-resistant ovarian cancer cells could explain in part the reduction in cell growth, invasion, and viability, and the increase in caspase-3 activity." (PMID 32260415, 2020). "In fact, studies in platinum-resistant ovarian cancer have shown that ILKAP, a phosphatase which inactivates ILK, is downregulated by cisplatin treatment, and that silencing ILKAP increases ILK activation and protects cells from cisplatin-induced apoptosis." (PMID 32260415, 2020). "ILK is coexpressed with and activates the pro-metastatic enzyme membrane type 1 matrix metalloproteinase (MT1-MMP) in epithelial ovarian cancer cell lines." (PMID 33256002, 2020). "We then determined the effect of ILK-1 high expression on stage III and IV ovarian cancer patients’ PFS in the TCGA database using Km plotter." (PMID 33256002, 2020). "The current data support MT1-MMP as an additional ILK substrate and show that modulation of ILK expression and activity inhibit MT1-MMP-related pro-metastatic behaviors of ovarian cancer cells." (PMID 26959113, 2016). "Co-expression of ILK and MT1-MMP was confirmed in a panel of ovarian cancer cell lines using real time quantitative PCR analysis." (PMID 26959113, 2016). "Evaluation of ILK and MT1-MMP mRNA levels in ovarian cancer cells supported the co-expression of ILK and MT1-MMP." (PMID 26959113, 2016). "EGF stimulation plays a role in matrix remodeling through the ERK and ILK/GSK-3 pathways in ovarian surface epithelial cells, and the combined targeting of endothelin and EGF receptors has been shown to increase antitumor activity in ovarian cancer." (PMID 38031074, 2023). "MT1-MMP activity enhances ovarian cancer cell penetration of meso-mimetic cultures; however the effect of ILK on this process has not been previously examined." (PMID 26959113, 2016). "Moreover, Akt, the most extensively studied downstream target of both ILK and PDK1, has also been shown to be overexpressed in ovarian carcinomas." (PMID 18349831, 2008).